IRF3 (interferon regulatory factor 3)
Diseases named in the same sentence as IRF3 in open-access papers (continued):
Sharing a sentence is not in itself a finding about the gene and the disease.
tumor (continued). "Furthermore, upon treating various types of tumour cell lines with FOXO1 inhibitors, we observed not only the upregulation of VEGFC, PD‐L1 and CCL4 but also varying degrees of increase in MOMP‐related molecules (such as BAX, BAK1, CASP3, STING, IRF3 and RELB)." (PMID 38899748, 2024). "We did not observe diminished expression of other immune sensors MAVS and MyD88 or downstream components of these immune pathways TBK1 and IRF3; suggesting that targeting of STING-specific immune responses may be an important strategy to facilitate tumor progression in HPV+ HNSCCs." (PMID 38147007, 2024). "The activated IRF3 dimer translocates to the nucleus and activates the transcription of type I interferon (IFN-I) and IFN-stimulated genes, promoting the cellular secretion of IFN-I.The most direct effect of IFN-I is to induce dendritic cell (DCs) maturation and mediate anti-tumor immunity." (PMID 39464890, 2024). "We find that high expression and T404 phosphorylation of STAT2 inhibit STING subcellular translocation and reduce the production of IRF3-dependent cytokines, including IFNs and T cell chemotaxis, without inhibiting IL-6 production, thus promoting tumor cell survival." (PMID 37036972, 2023). "In addition to its well-characterized role in the activation of the immune response via the IRF3/NF-KB pathway, TLR3 is emerging as a potential anti-tumor target in cancers, due to its ability to induce different death signals, depending on the cellular context." (PMID 37414800, 2023). "The enhanced TBK1 and IRF3 activation should increase the sensitivity of TYST cells to CD8+ T‐cell‐mediated killing in the co‐culture system while cGAS silencing usually attenuated the cGAS‐STING signaling to reduce IFN‐β production and CD8+ T‐cell infiltration, promoting tumor growth." (PMID 37986544, 2023). "IRF3 expression levels differed significantly between tumor stages (p = 0.0173 < 0.05), whereas the expression levels of the other IRFs did not alter significantly among tumor stages." (PMID 35664436, 2022). "Furthermore, we did not observe any change of YAP activation in the absence of IRF3 in the colon and tumor tissue from mice upon AOM/DSS treatment." (PMID 33188184, 2020). "Thus, phosphorylated TBK1 (pTBK1) and production of specific cytokines downstream of IRF3, such as CXCL10, can be measured as a function of STING activation, which plays important roles in tumor cells, antigen presenting cells, and potentially other cell types." (PMID 33013881, 2020). "These treated mice are not completely equivalent to the transplanted ones, in terms of DMXAA-induced IRF3 phosphorylation and IFNα production, and there are obviously other differences between the two tumor models, which have no reason to all be TGFβ-dependent." (PMID 31511510, 2019). "Similarly, IRF3/7 overexpression in RTT tumours did not attenuate PGE2 production." (PMID 39604727, 2025). "Our results demonstrated that deletion of B2R translates into robust IRF3 pathway activation without affecting viral replication, and in turn this activation translates into improved antitumor activity and increased T-cell responses against tumor antigens in mouse tumor models." (PMID 37016144, 2023). "In consistent, we found that the protein expressions of STING, cGAS, p-IRF3, p-TBK1, and PD-L1 were increased in the irradiated tumor although the protein expressions of IRF3 and TBK1 were not increased." (PMID 35847556, 2022). "Tumor formation assays in nude mice with IRF3-knockout HCT116 cells, with or without IRF3 rescue, revealed that reintroduction of IRF3, IRF3-ΔnDB, or IRF3-ΔNLS, but not the IRF3-5D, exhibited faster growth." (PMID 33188184, 2020).
tumor (continued). "We employed an RNA-sequencing approach to interrogate the pathways differentially regulated in distal colon and tumor tissues, upon AOM treatment and in the presence or absence of IRF3." (PMID 33188184, 2020). "The decreased F4/80+ macrophages and reduced tumor growth in Zyxin−/−;Irf3−/− mice suggested that the enhanced antitumor immunity observed upon Zyxin depletion was at least partially independent of the TBK1-IRF3 axis." (PMID 39304793, 2024). "Thus, 2pHLIP-dMSA induced transient tumor-targeted increases of type I interferon, IFN-β, and the pro-inflammatory cytokines TNF-α and IL-6, indicating activation of the NF-kB and IRF3 signaling pathways, without systemic activation." (PMID 38495104, 2024). "Further validation through Western blot and immunofluorescence analyses demonstrated that Poly(I:C) treatment increased expression of TLR3, p-IRF3, and IFN-β in tumor tissues in the Poly group compared to the no-Poly group, confirming successful activation of the TLR3-IRF3-IFN-β pathway." (PMID 39791120, 2024).
cancer (125 papers, 2010 to 2026). A tumor composed of atypical neoplastic, often pleomorphic cells that invade other tissues. "We further assessed the relationship between IRF risk scores and immune and stromal scores in cancer patients to examine why increased IRF3 and IRF7 expression promotes immune cell recruitment without killing tumors." (PMID 34488791, 2021). "IRF3 as a transcription factor has been reported as a regulator in type I interferon genes playing a vital role in mammalian response to pathogens and considered to be implicated in various biological pathological conditions, including cancer." (PMID 31543899, 2019). "In cancer, diABZI analogs, demethylating agents, or IRF3 activators can selectively reactivate silenced circuits." (PMID 40607404, 2025). "IR700 loading boosted ICD induction in cancer cells upon irradiation and transactivated the cGAS/STING/IRF3/IFN‐I axis in TAMs by promoting the release of endogenous dsDNA from dying cancer cells." (PMID 40240911, 2025). "Seven of the identified HGs (HK2, SRSF10, SOD1, ERO1L, IRF3, MME, and SH3BP5) were associated with PE and various carcinomas." (PMID 40966654, 2025). "Previous studies have identified IRF3 as a regulator of IL-33 in vitro; however, we demonstrate that IL-33 is the target of TBK1-IRF3 signaling activation in cancer-prone chronic inflammation." (PMID 38816352, 2024). "Treatment of THP1 reporter cells in co-cultures with SKBR3 (HER2 + ) or OVCAR3 (NaPi2b + ) cancer cells with the Fc-wt ADCs induced IRF3 reporter activity more potently compared to the free payload." (PMID 38992037, 2024). "These hybrids, referred to as R-loops, also stimulate cGAS, and subsequently, IRF3, culminating in apoptosis, especially in BRCA1 (BReast CAncer susceptibility gene 1)-mutated cancer cells in vitro." (PMID 38139802, 2023). "Mutations or abnormal expression levels of specific genes in the RLR signaling pathway, such as MAVS, TBK1, and IRF3, can lead to changes in the immune signaling pathway, resulting in a decreased ability of immune cells to recognize and clear malignant tumors." (PMID 38099311, 2023). "Recent studies have revealed that the innate immune system pathway, cGAS/STING/IRF3, plays a critical role in DNA damage response and immune regulation in various cancers." (PMID 38057852, 2023). "While, upon DNA damage, in cancer cells the enzyme directly interacts and crosslinks the IRF3 protein by limiting its transcriptional activity in the dying cells." (PMID 36572679, 2022). "Currently, several therapeutic approaches aim to stimulate cGAS/STING/IRF3 pathway in cancer to promote an over-stimulation of IFN I." (PMID 36572679, 2022). "cGAS gene expression is well correlated in many cancer types, while TBK1 and IRF3 gene expression is correlated with immune cells presence and interferon response only in few specific cancer types." (PMID 35794238, 2022). "Among the top enriched transcription factor motifs, we identified JUN, ETV5, and IRF3, that are well-known to be involved in cancer development." (PMID 35130920, 2022). "To examine STING activity in different human cancer cells, we first analyzed IRF3 nuclear localization in several human cancer cells upon activation of STING." (PMID 33790360, 2021). "In this context, engulfment of cancer cells is unable to activate the cGAS-STING-interferon regulatory factor 3 (IRF3) axis or induce type I IFN production to augment the ability of DC1s to cross-present antigens." (PMID 34290401, 2021). "The innate immune STING signal defends against viruses and cancers potently and rapidly, accompanied by the phosphorylation of the transcription factor IRF3 by kinase TBK1 and then the production of type I IFNs." (PMID 34299262, 2021).
cancer (continued). "This upregulation of IFNβ1 after treatment with cytotoxic agents goes in line with previous studies that have shown that high levels of damage in cancer cells after treatment results in the activation of the STING/IRF3 pathway and drives IFNβ1 expression." (PMID 34298736, 2021). "This confirms that both NF-κB and IRF3 branches are frequently engaged in cancer cells upon genotoxic treatment." (PMID 35087822, 2021). "Direct interaction between stromal fibroblasts and cancer cells also seems to drive resistance to oncolytic viruses as a result of the induction of a STING/IRF3-dependent inflammatory program in fibroblasts, which upregulates IFNβ1." (PMID 34298736, 2021). "IHC confirmed these results and suggested that the IRF3 protein was more highly expressed in cancer tissues than that in normal tissues." (PMID 34488791, 2021). "In this study, we explained the anti-cancer effect of miR-365 in gastric precancerous lesions via regulation of the TLR4/IRF3/YAP/CDX2 axis." (PMID 33292210, 2020). "The cGAS-STING, TBK1, and IRF3 increasingly express in pan-cancer cells, and their gene expression level negatively correlates with their methylation in most cancer types." (PMID 33643304, 2020). "It has been reported in the literature that TLR4 promotes the occurrence of cancer by regulating the expression of the downstream protein interferon regulatory factor 3 (IRF3)." (PMID 33292210, 2020). "This culminates in the activation of IRF3 and NF-kB to promote an adaptive T-cell response against cancer cells." (PMID 32477956, 2020). "Scriptaid treatment enhanced the spread of the P/V-CPI- virus through a population of cancer cells, and suppressed interferon-beta induction through blocking phosphorylation and nuclear translocation of Interferon Regulatory Factor 3 (IRF-3)." (PMID 31083335, 2019). "Oshita et.al observed higher expression of IRF-3 in tumors of surviving patients with stage I NSCLC than that in patients who succumbed from cancer." (PMID 29100282, 2017). "In some cases, other alterations downstream of STING precluded cancer cells from activating the transcription factors IRF3 or NF-κB36." (PMID 28598415, 2017). "The proposed master regulator TBK1 is a member of the non-canonical IκB protein kinases which is involved in the activation of IRF3 and c-Rel and NF-κB in cancer." (PMID 27092172, 2016). "Notably, IRF3 functions as a transcription factor regulating IL-33 expression in cancer-prone chronic inflammation, making it a potential target to inhibit chronic inflammation and cancer development." (PMID 40647388, 2025). "A pan-cancer analysis revealed that high activation of the cGAS-STING pathway and its downstream signaling components such as TBK1 and IRF3 is associated with reduced immune cell infiltration in the TME and poor prognosis for colorectal and gastric adenocarcinomas." (PMID 38999073, 2024). "Transcription factor (TF) motifs, including CEBPB (+), FOSB (+), SAP30 (+) and ATF4 (+), were significantly upregulated in CNV high cancer cells, while IRF3 (+), ETV7 (+), STAT1 (+) and IRF7 (+) were downregulated, indicating promising new regulatory networks driven by TFs in OS cells." (PMID 36596773, 2023). "To investigate whether the identified PARP7/FRA1/IRF1/IRF3 axis is observed in other cancer cell lines, we compared FRA1 and PARP7 expression levels across 1,078 cell lines from various origins using the DepMap project dataset." (PMID 38011562, 2023). "Additionally, H3K4me3 was also enriched to the motifs bound by transcription factor families linked to cancer immunity in CFP1-knockdown cells, such as IRF3 and IRF820,21." (PMID 37735441, 2023).
cancer (continued). "Activation of NF-κB induces inflammatory cytokines and MMP secretion, which may promote cancer progression, whereas activation of IRF3 induces the production of type I interferon, which leads to apoptosis of cancer cells." (PMID 36365103, 2022). "The positive cells of senescence-associated β-galactosidase staining and cGAS, STING, interferon-regulatory factor 3 (IRF3), and signal transducer and activator of transcription 6 (STAT6) expression levels using immunostaining were elevated in HGD and in cancers." (PMID 36061145, 2022). "Prompted by these results, we questioned whether the IRF3 covalent dimers could be assembled in dying apoptotic cancer cells." (PMID 36572679, 2022). "IRF3 was reported to participant in the innate immune response against cancer via STING pathway." (PMID 35012444, 2022). "Our analysis of mutation rates showed that the four STING pathway genes (cGAS, STING, TBK1 and IRF3) were usually not mutated in human cancers, with a complete absence of homozygous loss-of-function mutations in almost all cancer types." (PMID 35794238, 2022). "Interestingly, here we demonstrated that in cancer cells the enzyme is also able to regulate the IRF3 pathway using a different modality, hence acting as cross-linking enzyme and leading to the covalent IRF3 dimerization." (PMID 36572679, 2022). "In order to promote the activation of this pathway, we constructed a series of oncolytic VACVs combining the deletion of the thymidine kinase gene (to achieve selective replication in cancer cells) with targeted inactivation of selected genes interfering with IRF3 pathway activation." (PMID 34553028, 2021). "This concurrent induction of Il-6, Rsad2 and Ifit1 by CPT in TC-1 cells prompted us to broadly assess whether such convergent induction of the NF-κB and IRF3 branches was a frequent response to DNA damage in cancer cells." (PMID 35087822, 2021). "IRF3 plays important roles in DNA damage responses (DDRs) in cancer." (PMID 34488791, 2021). "In addition to screening cancer cell lines, we previously immortalized IRF3+/+ and IRF3−/− primary MEFs derived from C57Bl/6 mice." (PMID 27809273, 2016). "On the other hand, it has been shown that TLR3 and IRF-3 were down-regulated in a subset of human PCa tissues and that TLR3-downregulation was associated with recurrence, suggesting a successful immune system escaping strategy for some advanced cancers." (PMID 25444175, 2015). "However, previous data have stated that IRF3-dependent apoptotic pathway in both virus infected and cancer cells is triggered only by the activation of dsRNA-sensing cytoplasmic receptors and not by endosomal receptor TLR3." (PMID 25444175, 2015). "Similarly, IR could also be sufficient to induce a robust immune response via IRF3 phosphorylation downstream of dsRNA recognized by RIG-I/MDA5 in AR– cancers in which IKKε is readily expressed." (PMID 41542764, 2026). "This is consistent with the sensing of genomic damage of cancer cells by fibroblasts, which resulted from transcytosis of cytoplasm from cancer cells into neighboring fibroblasts and activation of the stimulator of interferon genes–interferon regulatory factor 3 pathway." (PMID 40877413, 2025). "However, a pan-cancer analysis has demonstrated that elevated activation of the cGAS-STING pathway, particularly of IRF3, is associated with poor prognosis in patients diagnosed with specific types of cancer, including colorectal, prostate and lung adenocarcinomas." (PMID 38203626, 2023). "Additionally, the ability of STING to activate downstream targets, such as IRF3 or NF-κB, can also be compromised in cancer cells, but this occurs via unknown mechanisms." (PMID 32774773, 2020). "Mechanistically, AOH1996 induced cellular DNA damage, activated the cGAS–STING signaling pathway, suppressed cancer stemness by upregulating p-TBK1 expression, and promoted CD8+ T-cell-recruiting chemokines by stimulating IRF3-mediated transcription." (PMID 41024256, 2025).